MTOR (mechanistic target of rapamycin kinase)
Diseases named in the same sentence as MTOR in open-access papers (continued):
Sharing a sentence is not in itself a finding about the gene and the disease.
tumor (continued). "Although this is not the first study to show that cardamonin suppresses mTOR and NF-κB signaling, to our knowledge, cardamonin-mediated reduction of mTOR and NF-κB levels in PDC as a potential anti-tumor mechanism has been demonstrated for the first time." (PMID 33234722, 2020). "In contrast, ILC1s in the tumor microenvironment exhibit increased TNF production, which is independent of mTOR and glycolytic pathways." (PMID 32983138, 2020). "The treatment in the model system made it obvious, that the effect of the mTOR inhibition was a slowdown of the proliferation in CEA424-SV40 T antigen transgenic mice, but not a cytotoxic effect on the tumor cells and a cure for the mice." (PMID 32373532, 2020). "The phase II study EVOLVE-1 did not demonstrate any benefit of the mTOR inhibitor everolimus on the treatment of advanced HCC, and tumor heterogeneity was suggested as a possible explanation for the poor performance of targeted therapies." (PMID 32520221, 2020). "Although it is not entirely clear whether especially senescent tumor cells are sensitive to the oncolytic activity of rapamycin, generally speaking, senescent as well as non-senescent cells with high metabolic activity might share increased dependence on the mTOR pathway for their survival." (PMID 31354486, 2019). "We suggest that AKT/TWIST/mTOR pathway should be targeted to affect (i) CSC survival, (ii) “bulk” tumor cells, and (iii) the non-CSC to CSC reversion phenotype (using additional CSC cell lines)." (PMID 31357505, 2019). "Lesions never carried both ‘MAPK/mTOR’ and ‘AKT/mTOR’ signatures, indicating mutual exclusivity, consistent with the low OL of pERK and pAKT expression in ASC tumours." (PMID 31772293, 2019). "In the subgroup analysis, expression levels of eIF4E, p-PI3K, p-AKT, p-mTOR, p-4EBP1, p-eIF4E, p-S6K1, and p-S6R in the tumor specimens of patients with or without recurrence were analyzed using IHC staining and quantified by semi-quantified scoring systems." (PMID 31756179, 2019). "Until recent years, PTEN was not considered according to its high tumor suppressor value by the research community, while at the same time the downstream signaling network, and especially the PI3K/mTOR/Akt pathway, received enormous attention." (PMID 31404976, 2019). "Taken together, our data demonstrate the anti-tumor activity of elacestrant, as a single agent, and/or in combination with inhibitors of the PI3K/mTOR pathway, in models derived from patients who did not benefit from palbociclib treatment in the clinic." (PMID 31852484, 2019). "Thus, in the Prlr knockout mice, the loss of negative feedback signaling on the lactotroph cell involving PRLR and diminished or absent STAT5 signaling is likely to be driving tumor development, whereas in humans, activation of the mTOR/Akt signaling may represent an alternate tumorigenic mechanism." (PMID 30445560, 2019). "Other signalling pathways significantly deregulated in AFP-high tumours and worthy of further analysis include IGF2–IGFR, mTOR, NOTCH and BAP1." (PMID 31285588, 2019). "Reports suggest that niclosamide inhibits tumor growth promoting pathways, including WNT/beta-catenin, STAT3, Notch, and mTOR pathways, however, its exact antitumor mechanism is not entirely clear." (PMID 30258081, 2018). "Cell lines engineered to harbor PIK3CA mutations in the ‘hotspots’ responded more favorably to PI3K/mTOR dual inhibition than PI3K inhibition only, indicating that tumor survival is not strictly dependent on the activated PI3K." (PMID 31093356, 2018). "While neither PI3K nor mTOR inhibitor drug treatment alone suppressed tumour growth in WHIM20 completely, the combination of both PI3K and mTOR inhibitors significantly reduced tumour growth to a nearly static state." (PMID 28348404, 2017). "We show that the G116A mutation impaired GABARAPL1 function in autophagosome/lysosome fusion and inhibited lysosome activity but did not alter MTOR and ULK1 activities or tumor growth in vivo." (PMID 28915569, 2017).
tumor (continued). "The immunostaining score for p-mTOR (p<0.05) was significantly higher in G1/G2 tumors than in G3 in GEP-NETs, while it was not significantly correlated to tumor stage in MTCs." (PMID 26934559, 2016). "Accordingly, three RCC cell lines were driven to non-responsiveness towards the mTOR-inhibitor everolimus and the influence of SFN on tumor growth, proliferation, and motility of everolimus-resistant and everolimus-sensitive tumor cells was compared." (PMID 27863441, 2016). "Expression of an activated form of mTOR prevented drug-induced phosphorylation of ATG13 S318, prevented autophagosome formation, and significantly reduced tumor cell killing (data not shown)." (PMID 27379204, 2016). "As opposed to in vivo tumor repression, where single agent LET and MK-8669 were significantly better than MK-0646, ER (51 genes) and mTOR (160 genes) inhibition altered few genes compared to IGF blockade (1,163 genes)." (PMID 27765027, 2016). "In our tumor samples, the phosphorylation status of Akt did not correlate with the activity of the PI3K/mTOR inhibitor." (PMID 26284517, 2015). "Expression of p-mTOR, pS6, p4EBP1, and MMP7 was elevated in primary tumor tissue as compared with that in adjacent noncancerous gastric tissue." (PMID 25909163, 2015). "While NVP-BEZ235, a dual pan-PI3K and mTOR inhibitor, led to marked tumor regression in the PIK3CA-GEMM, it did not affect tumor growth significantly when treating the Kras-GEMM unless it was used in combination with a MEK inhibitor." (PMID 22666248, 2012). "It is possible that the resistance of RAS mutant tumour lines in this study and others is the result of compensatory signalling by a parallel or non-canonical pathway, such as PI3K/Akt/mTOR." (PMID 23039341, 2012). "There are also several drugs in development (so are not FDA approved) with single agent activity in TSC tumor models; these include a MEK1/2 inhibitor (CI-1040) and a dual PI3K/mTOR inhibitor (NVP-BEZ-235)." (PMID 20146790, 2010). "In contrast, mTOR, IGF1R and JAK/STAT pathways appeared to be primarily important for growth, branching and differentiation of both normal and tumor cells, regardless of the cell culture conditions, ECM and the microenvironment." (PMID 20454659, 2010). "There are not significant relationship between mTOR and PTEN gene expression levels and patients' age, gender, pathological type, differentiation, lymph node metastasis, except tumor size." (PMID 20673489, 2010). "Of the 10 tumours that overexpressed PLD1, 5 were negative for phospho-Akt expression, and importantly, these 5 PLD1-positive tumours overexpressed phospho-mTOR (tumours 6–10)." (PMID 17726467, 2007). "Data from our study identify an additional subset of patients with tumours that overexpress PLD1 and phospho-mTOR, but do not express constitutive levels of phospho-Akt." (PMID 17726467, 2007). "Additionally, the downregulation of tumor-promoting pathways, including PI3K-Akt, mTOR, and TGF-β signaling, indicated that this phototherapy not only enhanced immune activation but also suppressed immune evasion mechanisms." (PMID 40283929, 2025). "Interestingly, MAPK4 was demonstrated to promote tumours through direct and specific activation of AKT/mTOR via an alternative pathway without dependence on PI3K/PDK1." (PMID 40845073, 2025). "Additionally, alterations in downstream signaling pathways, including PI3K/AKT/mTOR and cyclin D1/CDK4/6, can promote tumor growth independent of estrogen signaling." (PMID 40566067, 2025). "Additionally, we observed a negative correlation between EPCART and PDCD4 in PCa tumor samples, suggesting there to be a subpopulation of PCa tumors, the protein synthesis of which is modulated by EPCART through AKT/mTOR/PDCD4 pathway." (PMID 39147845, 2024). "The mTOR pathway was mildly activated in all ACTH-PAs.EVE monotherapy and combination therapies could not control tumor growth and ACTH secretion." (PMID 39736867, 2024).
tumor (continued). "The PI3K/AKT/mTOR signaling pathway could be inhibited by BYL-719, and the Notch, JAK-STAT and MAPK/ERK signaling pathways which have crosstalk in the tumor microenvironment (TME) are also inhibited." (PMID 39469631, 2024). "However, a recent meta-analysis has highlighted the potential benefits of mTOR inhibitors as adjuvants in combination therapies for HNC, though further research is required as these drugs did not induce significant tumor responses when administered alone." (PMID 38612819, 2024). "Four compounds, methotrexate and pralatrexate (folate antagonists), temsirolimus (mTOR inhibitor), and GSK2126458 (PI3K inhibitor), were confirmed to reduce tumour size, but did not synergize with trametinib at the various doses tested, and therefore were not further analysed." (PMID 36861754, 2023). "Tumour heterogeneity is a common phenomenon in GEP-NENs and has a negative impact on treatment success and prognosis as it produces cell clones that do not express treatment targets (i.e., SSTR, mammalian target of rapamycin–mTOR- signalling pathway, Ki-67)." (PMID 36980746, 2023). "Similarly, the inhibition of mTOR (oral gavage for 21 days-3 mg/kg twice daily 3 x/week in EWS and RMS, or 2.5 mg/kg, daily) in OS resulted in tumor volume reduction, without observable side effects." (PMID 36839989, 2023). "This strong signal with MK2206 is not surprising as ROR1 signaling activates the PI3K/AKT/MTOR pathway and high-level expression of ROR1 may mitigate the anti-tumor activity of an AKT inhibitor in combination with chemotherapy." (PMID 37029329, 2023). "For instance, mTOR inhibition can promote negative feedback in which S6K is able to phosphorylate Insulin receptor substrate 1 (IRS1) with the subsequent activation of PI3K and tumor growth." (PMID 37237486, 2023). "This suggests a mode of tumor progression for GBM cells, which may transform, rather than merely substitute, surrounding tissue; such a phenomenon is sensitive to mTOR inhibition." (PMID 35326570, 2022). "Moreover, other report showed that using WES for pre‐treatment and post‐treatment tumor samples in six RCC cases, genetic alterations involving mTOR pathway were not newly acquired through mTOR inhibitor treatment." (PMID 33107222, 2021). "The result suggests that mTOR and c‐Myc, but not VEGFC, were involved in tumor growth." (PMID 33128283, 2021). "However, the mTOR inhibitors can activate AKT by interrupting a negative feedback regulatory loop, resulting in their anti-tumor activity attenuated in patients." (PMID 34395258, 2021). "Finally, it is worth mentioning that mTOR alterations and defective ATG are also bound to several non-tumoral cells, which support tumor growth and mediate GBM relapse and infiltration." (PMID 33092261, 2020). "We demonstrate that GIC‐secreted factors are sufficient to increase mTOR activity in microglia, although this does not exclude the possibility that factors secreted by other cells, including non‐GIC tumour cells, may contribute to this phenotype." (PMID 32567735, 2020). "Mechanically, the tumor-suppressive functions of AIM2 in CRC were mediated through its participation in repressing the AKT/mTOR pathway, and the inactivated AKT/mTOR failed to increase Gli1 protein expression, resulting in the inhibition of cell proliferation and migration." (PMID 33291082, 2020). "The mTOR inhibitor RAPA is used in transplant patients to prevent allograft rejection; however prolonged RAPA treatment can promote Akt activation through the withdrawal of negative feedback loop, and thus can facilitate tumor growth." (PMID 32635337, 2020). "Interestingly, in different tumor models (i.e., thymoma and melanoma) the lack of SIRT1 in MDSCs fuels the glycolytic pathway through the mTOR-HIF-1α pathway." (PMID 31130949, 2019).
tumor (continued). "Among other processes that can be associated to an AMPK-dependent positive modulation of Forkhead box O3 (FOXO3) and a negative modulation of mTOR/AKT, MET may specifically act on tumor-initiating GSC cells." (PMID 31214505, 2019). "However, not all tumor suppressor genes involved in axon regeneration in our initial screen, indicating the unique role of PTEN/mTOR in determining the neuronal intrinsic regenerative ability." (PMID 30158848, 2018). "In addition, the entire mTOR pathway is highly negatively regulated by the phosphatase and tensin homolog gene (PTEN), an upstream tumor suppressor that blocks PI3K signaling when it is not phosphorylated." (PMID 28192480, 2017). "We found that CD44- and SOX2-positive CSCs were inhibited if we inhibited mTOR signaling, which prevents the proliferation of NPC cells and reduces secondary tumor volume and weight, but OCT4-positive CSCs were not significantly affected either in vitro or in vivo." (PMID 26202311, 2015). "However, in tumor variants with a high intrinsic tumor level of PI3K/Akt/mTOR, MFP as a single agent did not induce tumor regression, and its combination with PI3K/mTOR inhibitors is required to induce a therapeutic response." (PMID 26098779, 2015). "While there was no single pathway significantly up-regulated in all three tumor models, there were some pathways up-regulated in two models, such as proteasome in the xmrk and Myc models, and IGF1 pathway, mTOR pathway, tRNA biosynthesis and focal adhesion in the xmrk and kras models." (PMID 24633177, 2014). "Even though previous studies with genetic targeting of IKKβ in tumor mouse models did not address the effect of IKKβ deletion on tumor angiogenesis, it has been demostrated that IKKβ can promote tumor angiogenesis by phosphorylating TSC1 and activating mTOR in tumor cells." (PMID 24955217, 2014). "If so, mTOR inhibition would not be a useful adjunct to TMZ therapy in a clinical setting and could exacerbate tumour growth." (PMID 24909675, 2014). "In conclusion, p-mTOR expression in non-tumour umbrella cells is likely a reflection of their metabolic plasticity, and extension to the inner layers of the urothelium in NMI tumours is consistent with an enhanced malignant potential." (PMID 25202348, 2014). "This will require multiple biopsies of individual primary and secondary tumours; to date, there are no published data using this approach in mRCC but it is a method being utilised in the PREDICT consortium's pre-operative trials of mTOR and kinase inhibitors." (PMID 22738081, 2011). "To address whether CD133- cells can be converted to CD133+ tumor cells without adding exogenous TGF-β, and if so, whether mTOR signaling is involved in the process, we employed a single-cell long-term culture system." (PMID 22145042, 2011). "Furthermore, inhibition of mTOR (TorTED) using repo-GAL4 did not significantly affect Path-GFP expression in the surface glial of tumor brains, suggesting that mTOR likely functions downstream of Path to regulate glial proliferation and tumor growth." (PMID 41252380, 2025). "Also, mTOR seems to differentially regulate MCL-1 in tumor and normal cells, therefore we could not see MCL-1 downregulation even after efficient mTOR inhibition in NHBE cells." (PMID 36588105, 2023). "Since the primary indication for mTOR inhibitor selection was in vitro CRP rather than molecular variations, ETA thus identified several patients (n = 13) with in vitro and largely in vivo response to mTOR inhibition, but where the tumor harbored no known alterations indicative of mTOR activation." (PMID 33935721, 2021).
tumor (continued). "Although the PI3K/Akt/mTOR pathway benefits most viruses, the PI3K/Akt/mTOR pathway has been shown to reduce HBV replication in some experimental conditions and may be partly responsible for low or absent HBV replication in transformed and tumor cells." (PMID 34580816, 2021). "However, both mTOR complexes inhibition, rather than mTORC1 and PI3K inhibition, depletes SOX2 and OCT4 protein levels in glioblastoma cells and suppresses the ability to form tumor-spheres as well." (PMID 33828530, 2021). "Although FAK inhibition could abrogate the effects of NLG3, its therapeutic capacity is limited due to low permeability in infiltrative tumours such as DMGs; as yet, PI3K/AKT/mTOR pathway inhibitors have not been explored for their potential to attenuate synaptic communication within this setting." (PMID 34944870, 2021). "Considering the activation of downstream mTOR pathway, the maintenance of STAT3 phosphorylation occurred in WL group showed the leucine influence, since the group without tumour cells or bearing a tumour had constant levels of phospho-STAT3 over the three study days compared with the C group." (PMID 30975087, 2019). "Most recently, IHC analysis of nine mTOR-related biomarkers in patients with non-metastatic clear cell RCC was reported, which suggested that cumulative number of aberrantly expressed biomarkers correlated with aggressive tumor biology and inferior oncologic outcomes." (PMID 24886512, 2014). "In a mouse allograft model for KS, specific inhibition of the paracrine activation of mTOR in non-vGPCR-expressing cells was sufficient to inhibit HIF upregulation in these cells, and abolished the ability of the vGPCR-expressing cells to promote tumor formation in vivo." (PMID 21559457, 2011). "Although, a modest recovery of HIF-1α protein was visible after 2 hr of high oxygen exposure in GBM cells, but not in normal cells, indicating that tumour cells may re-establish HIF-1α level through a hypoxic independent mechanism, possibly controlled by mTOR progressive activation." (PMID 19587783, 2009). "PI3K upregulates HIF-1α protein synthesis via AKT/mTOR and the eukaryotic translation initiation factor 4E (eIF-4E) binding protein (4E-BP1) Nevertheless, the activation of AKT could also lead to increased HIF-1α expression in tumor cells via another pathway that is independent of mTOR activation." (PMID 34830491, 2021). "However, the immune-reactivity score for mTOR was higher in the tumor center of patients with evidence of distant metastases (p = 0.01), and MMP7 was more highly expressed in the tumors of patients with nodal involvement (tumor center: p = 0.01, invasive front: p = 0.019; data not shown)." (PMID 26652716, 2015). "Thus, mTOR inhibition appears to preserve while MEK inhibition appears to inhibit antigen-specific T-cell responses in immunogenic MOC1 tumors, potentially explaining the durable responses observed following mTOR but not MEK inhibition in immunogenic MOC1 tumor bearing mice." (PMID 26506415, 2015). "On the basis of the results present here, we speculate that tumor level and localization of PI3K/Akt/mTOR pathway activation before neo/adjuvant therapy can be used to predict which patients will benefit with a combination therapy with PI3K/mTOR inhibitors and which patients will not." (PMID 26098779, 2015). "However, based on the well-described negative effect of AMPK on the mTOR pathway in other tissues, it is tempting to speculate whether AMPK activation also promote mTORC1 inhibition in normal thyroid cells, as well in the different tumours derived from the thyroid follicular cell." (PMID 27919039, 2014).